CXCR4 (C-X-C motif chemokine receptor 4)
Diseases named in the same sentence as CXCR4 in open-access papers (continued):
Sharing a sentence is not in itself a finding about the gene and the disease.
colorectal cancer (continued). "For example, expression of CXCR4 in the vasculature of hepatocellular carcinoma has been correlated with poor prognosis, whereas CXCR4-positive microvessels were significantly associated with tumor growth and UICC stages in gastric and colorectal cancer." (PMID 34793563, 2021). "Therefore, the expression of CXCR4 gene in colorectal cancer is also significantly correlated with tumor recurrence, liver metastasis and prognosis of patients." (PMID 34930323, 2021). "Previous studies have shown that H19 promotes cancer development through different mechanisms, as examples: in gastric cancer through Fas-related protein, in cholangiocarcinoma through IL-6 and CXCR4, in colorectal cancer through HMGA1, and in multiple myeloma through P50/P65." (PMID 34843522, 2021). "Together, these results suggested that the autocrine IL-1α and paracrine CXCL12 co-enhances the metastatic potential of colorectal cancer cells; IL-1Ra can inhibit the metastatic potential of colorectal cancer cells via decrease IL-1α/CXCR4/CXCL12 signaling pathways." (PMID 34930323, 2021). "In addition, this agent, as a potent CXCR4 antagonist, shows relevant pro-apoptotic effects in tumor tissues in a mouse model of human colorectal cancer." (PMID 34208189, 2021). "Therefore, to extend our understanding of CXCR4 regulation in colorectal cancer, we separated colonocytes from stromal cells and examined their CXCR4 expression levels compared to their control counterparts." (PMID 32110952, 2020). "The same comparative biodistribution study was performed in an alternative M5 tumor cell line-derived subcutaneous CXCR4+ colorectal cancer mouse model in order to determine if the previously observed biodistribution changes were replicated in a completely different tumor model." (PMID 33105866, 2020). "In colorectal cancer, it was found that overexpression of CXCR4 could promote the infiltration of myeloid-derived suppressor cells (MDSCs)." (PMID 33289699, 2020). "The chemokine receptor CXCR4 is overexpressed and functional in colorectal cancer." (PMID 32708431, 2020). "Another meta-analysis of 25 selected articles involving 3796 patients with colorectal cancer confirmed that CXCR4 expression is related to tumor–node–metastasis (TNM) stage, tumor differentiation, liver metastasis, lymph node metastasis, distant metastasis, and reduced survival." (PMID 32260318, 2020). "In this context, different categories of T22‐GFP‐H6 ArtIBs were implanted subcutaneously (SC) in a CXCR4+ colorectal cancer mouse model, releasing fluorescent material from the implantation point, followed by selective uptake by a remote CXCR4+ tumor, with specific kinetics for each ArtIB type." (PMID 32042562, 2020). "Overexpression of CXCR4 and the administration of the agonist and inhibitor to β-catenin signal pathway were used to explore the mechanism of Astragalus membranaceus and Curcuma zedoaria in colorectal cancer treatment." (PMID 31275425, 2019). "Moreover, CXCR4 was remarkably expressed in the cytoplasm and membrane of colon cancer cells and RhoA was predominantly expressed in the cytoplasm of colorectal cancer tissues." (PMID 30678736, 2019). "According to the results from other reports that CXCR4 could be the key factor related to metastasis effects of colorectal cancer, so we overexpressed the CXCR4 in HCT116 cells." (PMID 31275425, 2019). "The SDF-1 is secreted by liver, and CXCR4 is highly expressed in the colorectal cancer cells." (PMID 31275425, 2019). "Colorectal cancer cells overexpressing CXCR4 showed the increased metastasis ability, but the overexpression of CXCR4 could slightly rescue the EMT signal when they were treated with HQEZ." (PMID 31275425, 2019). "Based on our results, it makes possible that in OXA and 5FU resistance colorectal cancer, CXCR4 mediated pathway-related proteins may be studied as potential markers in colorectal cancer samples." (PMID 27668882, 2016).
colorectal cancer (continued). "HIF-1α and CXCR4/CXCL12 have crucial roles in the metastatic process of colorectal cancer." (PMID 24629239, 2014). "However, recently published studies demonstrated that CXCR4 is expressed in nucleus of lung and colorectal cancers." (PMID 24659999, 2014). "Similarly, it has been reported that SDF-1α/CXCR4 signaling induced cell adhesion of endothelial progenitor cells and colorectal cancer cells." (PMID 25114911, 2014). "The aim of this study was to construct a lentiviral vector of CXCR4-siRNA (Lenti-CXCR4-siRNA) and investigate whether the vector can inhibit the growth, migration, invasion and hepatic metastasis of colorectal cancer (CRC)." (PMID 24647809, 2014). "In this study, we found that CXCR4 was a direct target of miR-133b in colorectal cancer." (PMID 24330809, 2013). "Colorectal carcinoma cells also express a higher level of CXCR4 than normal intestinal epithelias." (PMID 23443093, 2012). "For example, a nuclear CXCR4 expression, which was reported to be associated with lymph node metastases in colorectal cancer, was not seen in our series." (PMID 20386750, 2010). "Interestingly, as previously observed in colorectal carcinomas, 86 of 293 gastric carcinomas (29%) showed CXCR4 positive microvessels in the tumour stroma with a strong CXCR4 immunoreactivity of endothelial cells." (PMID 20386750, 2010). "Therefore, we examined the expression of SDF-1α and CXCR4 in colorectal cancers (CRCs) and their related lymph nodes (LNs), and investigated the relationship between this expression and clinicopathological features." (PMID 18443596, 2008). "Similarly, Schimanski and colleagues found thatSW480, SW620, and HT-29 colorectal carcinoma cells expressed CXCR4 protein, asdid colorectal carcinoma tissue samples.CXCL12 induced the chemotaxis of SW480 and SW620 cells." (PMID 18779872, 2008). "Importantly, the synergy between these dual signaling pathways (Wnt/β-catenin and SDF-1/CXCR4) has been reported in other cancers, including breast, bladder, lung, ovarian, and colorectal cancers; intrahepatic cholangiocarcinoma; and osteosarcoma." (PMID 40735647, 2025). "However, CXCR4 has been demonstrated to stimulate proliferation and invasiveness of many different tumors including prostate, breast, lung, melanoma, glioblastoma, lymphoma, and colorectal cancer." (PMID 34209026, 2021). "Previous study also demonstrated that integrin αvβ6 may contribute to targeted liver metastasis of colorectal cancer via the SDF-1/CXCR4 axis, and we should notice the phenomenon that serum ITGB6 expression was markedly increased in patients with liver metastasis." (PMID 34796117, 2021). "According to these results, we thought that HQEZ induced the phosphorylation of β-catenin and the following degradation of β-catenin could induce the downregulation of EMT signal and CXCR4 which were important to inhibitive effects of HQEZ on the metastasis ability of colorectal cancer." (PMID 31275425, 2019). "For example, APC promoter methylation may be a potential biomarker for the carcinogenesis of colorectal cancer, SMAD4 expression was a prognostic marker for survival in colorectal cancer patients, and the overexpression of CXCR4 reduced overall survival in colorectal cancer patients." (PMID 27504822, 2016). "However, the function and regulatory mechanisms of CXCR4/CXCR7 and the relationship between TLR4-MD-2 and CXCR4/CXCR7 in colorectal carcinoma is still unknown." (PMID 22180778, 2011). "During the process of liver metastasis in colorectal cancer, the interaction between MIF and its receptors, CD74 and CXCR4, is markedly intensified, promoting tumor cell invasion and migration." (PMID 41127012, 2025). "C-X-C Chemokine receptor type 4 (CXCR4) is the most widely-expressed chemokine receptor in more than 23 human cancer types, including colorectal cancer." (PMID 37378300, 2023). "In colorectal cancer cells, the CXCL12/CXCR4 axis regulates PTEN to induce M2 polarization by activating the PI3K/Akt signaling pathway." (PMID 35893797, 2022).
colorectal cancer (continued). "Previous studies have evaluated total protein or total mRNA expression of CXCL12 and its receptors CXCR4 and CXCR7 in stromal cells or colorectal cancer cells 32-34." (PMID 34976180, 2022). "Some studies have demonstrated reverse expression between CXCR4 and CXCL12 in colorectal cancer 35, 36, and CXCR4 expression correlated with poor prognostic survival outcomes." (PMID 34976180, 2022). "In this context, we have recently reported this high tumor selectivity using a CXCR4-targeted fluorescent nanocarrier, that displays the exact self-assembling nanoparticle structure of the nanotoxins, in HNSCC, colorectal cancer, and lymphoma models." (PMID 35120582, 2022). "Similar observations were obtained for colorectal cancer, where the expression of CXCL12 and CXCR4 was higher in lung metastases than in the primary focus." (PMID 36012171, 2022). "Three NSCLC cell lines, A549, H1650, and H1975, and one colorectal cancer cell line, SW620 (with different EGFR and CXCR4 expression) were chosen for comparison." (PMID 35269297, 2022). "circ-0056618 acts as a sponge molecule, adsorbs miR-206, up-regulates the expression of CXCR4 and VEGFA in colorectal cancer, and promotes cell proliferation, migration and angiogenesis." (PMID 34616746, 2021). "The aim of this study was to investigate the co-operative role of CXCR4/CXCL12 axis and IL-1Ra in metastatic processes mechanism by interactions between colorectal cancer cells and stromal cells in their microenvironment." (PMID 34930323, 2021). "All samples from patients with colorectal cancer reproducibly demonstrated the presence of L1CAM, CXCR4 and ALK4 -positive cells in the invasive front with histological evidence for cell dissemination." (PMID 33897875, 2021). "This study confirmed the relationship of miR-133b and CXCR4 in TSCC cells, which was reported in colorectal cancer by previous study." (PMID 32390763, 2020). "The NC incorporates a protein nanoparticle to selectively internalize in CXCR4+ AML cells by exploiting high CXCR4 overexpression in LSCs as compared to HSCs, similarly to a previous approach in colorectal cancer (CRC)." (PMID 32295630, 2020). "Activation of CXCR4, a chemokine receptor specific for stromal-derived-factor-1 (SDF-1 also called CXCL12), is highlighted in the development and the metastasis of colorectal cancers." (PMID 31275425, 2019). "CXCR4 antagonists potentiate ICI effect in HCC xenograft, in murine intraperitoneal papillary epithelial ovarian cancer and in murine colorectal cancer where NOX-A12, the CXCL12 antagonist L-RNA-aptamer, enhanced CD8 and NK infiltration." (PMID 31661001, 2019). "CXCR4, SMAD4, and KRAS coexpressed with hsa-miR-224-5p were enriched in pathway of Intestinal immune network for IgA production and colorectal cancer." (PMID 31073530, 2019). "A recent study showed that the addition of a CXCR4 antagonist also disturbs metastasis of colorectal cancer to the liver, and connected certain HSC-derived factors to the increased expression of CXCR4." (PMID 31263976, 2019). "B7-H4 siRNA can effectively inhibit proliferation, invasion, and migration of LOVO cells by targeting CXCL12/CXCR4 and JAK2/STAT3 signaling, which can serve as a new target for colorectal carcinoma treatment." (PMID 26078947, 2015). "Interactions between CXCR4 and its ligand CXCL12 have been shown to be involved in cancer progression in colorectal cancer (CRC)." (PMID 21349176, 2011). "Present data are consistent with those in previous reports describing a positive correlation between CXCR4 expression and lymph node metastasis in cases of non-small-cell lung cancer (NSCLC), nasopharyngeal cancer, colorectal cancer, and esophageal cancer." (PMID 20181250, 2010). "Transforming growthfactor-β (TGF-β) increases cell-surface CXCR4 protein expression on humanmelanoma cells and we have recently found that FGF-2 upregulates CXCR4 onhuman colorectal cancer cells (Bseso B and Blay J, manuscript in preparation)." (PMID 18779872, 2008).
colorectal cancer (continued). "In colorectal cancer, IL-1RA reduces cancer cell metastatic potential by inhibiting the CXCL12/CXCR4 signalling axis, suggesting that it may have anti-metastatic effects in certain cancers." (PMID 40892159, 2025). "The ability of curcumin to augment the antitumor effect of capecitabine in human colorectal cancer by modulating cyclin D1, COX-2, matrix metallopeptidase 9 (MMP-9), VEGF and C-X-C chemokine receptor type 4 (CXCR4), has been assessed by using an orthotopic mouse model." (PMID 37376060, 2023). "CXCR4 is known to be overexpressed in more than 23 human cancers, and a negative correlation between CXCR4 expression and OS has been shown in non-small cell lung cancer, colorectal cancer, renal cell carcinoma, and acute myelogenous leukemia." (PMID 37749552, 2023). "On the other hand, CXCR4 is the most widely-expressed chemokine receptor in more than 23 human cancers, including breast, ovarian, melanoma, prostate and colorectal cancer while expression is low or absent in many normal tissues." (PMID 37378300, 2023). "Histological analyses on several primary tissues revealed that L1CAM, CXCR4 and ALK4 (the Nodal-receptor) have a similar expression pattern (insets) and were anatomically localized in the bulk tumor and in the invasive front of colorectal cancer samples." (PMID 33897875, 2021). "Through in vitro evidence, overexpression of CXCR4 has been identified as a negative prognostic factor in colorectal cancer." (PMID 34209026, 2021). "Naked cuticle homolog 2 (Nkd2) small-interfering RNA (siRNA) and chemokine receptor 4 (CXCR4) expression plasmid were synthesized and transfected into curcumin-treated SW620 colorectal cancer cell lines, and the NKD2 and CXCR4 expression levels were determined." (PMID 34621313, 2021). "Our results suggest that IL-1Ra inhibits liver metastasis of colorectal cancer by inhibiting CXCL12, secreted by fibroblasts in colorectal microenvironment and blocking CXCR4/CXCL12 signal to enhance the proliferation, invasion and neovascularization of colorectal cancer cells." (PMID 34930323, 2021). "In colorectal cancer (CRC), upregulation of the C-X-C motif chemokine receptor 4 (CXCR4) is correlated with metastasis and poor prognosis, highlighting the need to further elucidate CXCR4’s regulation in CRC." (PMID 32110952, 2020). "The colorectal cancer cell line HT-29 endogenously expresses CXCR4 (~36% of cells are CXCR4-positive) while practically no CXCR7 is expressed in these cells." (PMID 28945785, 2017). "In colorectal cancer, CXCL12/CXCR4 axis could promote epithilial-mesenchymal transtion (EMT) and induce 5-fluorouracil (5-FU) resistance via up-regulating miR-125b-5p and enhancing autophagy." (PMID 28968424, 2017). "We have also found that another pro-inflammatory cytokine, tumor necrosis factor (TNF) α, up-regulated CXCR4 expression at both transcript and protein levels in nasopharyngeal carcinoma and colorectal cancer (data not shown)." (PMID 26176534, 2015). "In conclusion, siRNA targeting of B7-H4 effectively suppressed the proliferation, invasion, and migration of LOVO cells by inhibiting the effect of CXCL12/CXCR4 and the phosphorylation of JAK2/STAT3 on increasing the metastatic potential of colorectal carcinoma." (PMID 26078947, 2015). "In addition to their roles in chemotaxis, CXCR4 and CXCL12 have been shown to regulate anoikis in breast and colorectal cancers." (PMID 24941119, 2014). "Interestingly, recent studies have shown that overexpressions of the chemokine receptor CXCR4 and of VEGF were predictive of early distant relapse in stages II and III colorectal cancers." (PMID 24629239, 2014). "Initial characterization of HT29 and HCT116 human colorectal carcinoma cells shows expression of both CXCR4 and CXCR7 chemokine receptors with no detectable CXCL12 expression." (PMID 20877573, 2010).
colorectal cancer (continued). "Ottaianoand colleagues found that CXCR4 was overexpressed in human colorectal carcinomatissues compared to normal tissues.Cell-surface CXCR4 protein was also expressed at high levels on SW620,SW48, and SW480 colorectal carcinoma cells, and at moderate levels on Caco-2and LoVo cells." (PMID 18779872, 2008). "This point is particularly interesting to note due to the fact that it has previously been shown in colorectal carcinoma that when endogenous sources of CXCL12 are epigenetically silenced, these cells more readily metastasize compared to those that engage in CXCR4/CXCL12 autocrine signaling." (PMID 18001467, 2007). "Augmentation of CD4+ T cells, CD8+ T cells and CD49b+ NK cells, as well as increased expressions of IFNg, IL10, CXCR4, and reduced expressions of IL17, STAT3 screened from gene and protein levels, jointly create a microenvironment conducive to inhibit the progress of colorectal cancer." (PMID 37143538, 2023). "Thus, owing to the specific CXCR4+ targeting and effective cytotoxicity of DITOX, this nanoparticle can efficiently eliminate apoptotic-resistant CXCR4+ colorectal CSCs through pyroptosis, demonstrating a promising method for colorectal cancer therapy." (PMID 35673561, 2022). "Based on our idea that Nodal signaling regulates the aggressiveness of the tumor cells through L1CAM and CXCR4, we investigated whether inhibition of Nodal signaling by SB431542 translates into increased progression-free survival in pre-established colorectal cancers." (PMID 33897875, 2021). "Indeed, CXCR4 expression is an independent prognostic marker for several malignancies including: AML, multiple myeloma, squamous cell carcinoma, gastric cancer, renal cancer, hepatocellular carcinoma, and colorectal cancer (CRC)." (PMID 32110952, 2020). "Hence, we inferred that hsa-miR-224-5p-CXCR4/SMAD4/KRAS interactions play a pivotal role in the development of RSCOAD and LSCOAD by regulating pathway of intestinal immune network for IgA production and colorectal cancer." (PMID 31073530, 2019). "Moreover, inhibition of CXCR4 via plerixafor is in clinical trials for use with advanced pancreatic, ovarian and colorectal cancers (CAM‐PLEX NCT02179970, 2014) but not in HNSCC." (PMID 29959873, 2018). "After the injection of exosomes collected from a colorectal cancer cell line (HT-29) with liver-targeted metastatic properties, the mice implanted with Caco-2 cells (low metastatic colorectal cancer cell line) show an increase in the hepatic burden of metastasis via the SDF-1α/CXCR4 axis." (PMID 30148162, 2018). "Given that CXCR4 and CXCL12 have been shown to have an additional role in anoikis in breast and colorectal cancers, future studies addressing the possible possibility that the upregulation of CXCR4 by AEG-1 may also function to regulate anoikis are of interest." (PMID 24941119, 2014). "Although CXCR4 is known to regulate the PI3K/Akt and MAPK cascade, the specific mechanism by which chemoresistance occurs in colorectal cancer cells has not been adequately documented." (PMID 27668882, 2016).